NEK2 (NIMA related kinase 2)
Diseases named in the same sentence as NEK2 in open-access papers (continued):
Sharing a sentence is not in itself a finding about the gene and the disease.
cancer (163 papers, 2009 to 2026). A tumor composed of atypical neoplastic, often pleomorphic cells that invade other tissues. "NEK2 is abnormally overexpressed in a wide range of human cancers and is implicated in various aspects of malignant transformation, including tumorigenesis, drug resistance and tumor progression." (PMID 40385396, 2025). "This study explored the involvement of Never In Mitosis A (NIMA)-related serine/threonine protein kinase 2 (NEK2) in phosphorylating RhoGDI1 and its implications in cancer cell behavior associated with tumor progression." (PMID 39768163, 2024). "In this study, we investigated the involvement of NEK2 in phosphorylating RhoGDI1 and its implications in cancer cell behavior associated with tumor malignant progression." (PMID 39768163, 2024). "Although recent findings have demonstrated the involvement of NEK2 in metastatic activities of cancer cells, its precise underlying remains poorly defined." (PMID 39768163, 2024). "Despite the fact that many articles have proposed NEK2 as a therapeutic molecular target in the progression of various cancers, the mechanism underlying NEK2 effect on cell motility is unclear." (PMID 39768163, 2024). "NEK2 is regarded as a trustworthy target in cancer treatment, which is linked to tumorigenesis, migration, invasion and survival." (PMID 37233832, 2023). "Aberrant NEK2 expression in cancers has been associated with tumor cell proliferation, migration, invasion, drug/radio resistance, immune response, and poor prognosis." (PMID 37835513, 2023). "Our studies have also identified a large number of splice variants regulated by Sam68 and NEK2 that are possibly implicated in the regulation of cancer cell motility and invasiveness." (PMID 35530315, 2022). "Although NEK2 oncogenic activity in cancer has been primarily associated to the promotion of genome instability and aneuploidy, mounting evidence suggests its implication in the pro-tumoral regulation of alternative splicing." (PMID 35530315, 2022). "The overexpression of NEK2 has been found in various tumor types and cancer cell lines, and its expression is associated with rapid relapse and a poor outcome in multiple cancer types." (PMID 35095717, 2021). "NEK2 expression is associated with early relapse and poor prognosis in a number of different cancers." (PMID 34281234, 2021). "NEK2 is highly expressed in various tumor types and cancer cell lines which is associated with rapid relapse and poor outcome in multiple cancer types." (PMID 33190424, 2021). "Our previous studies have identified that NEK2 was the gene most strongly associated with inferior survival in MM and other cancers, suggesting that NEK2 is a potential therapeutic target in MM." (PMID 31955515, 2020). "Further, there is no research on the detailed regulatory mechanism associated with Nek2 and β-catenin in cancer." (PMID 31319849, 2019). "Because PKM2 is an essential enzyme for regulation of aerobic glycolysis in cancer cells, we further determine that NEK2 expression is increased in high-risk patients and positively correlates with aerobic glycolysis genes including HK2, ENO1, and LDHA." (PMID 28086949, 2017). "Elevated expression of NEK2 appears to participate in the initiation, maintenance, progression, metastasis of cancer and is positively associated with poor prognosis." (PMID 27764815, 2016). "Its subcellular localisation and protein stability are regulated by several crucial mitotic kinases, such as Plk1, Nek2, Cdc2 and Aurora B. Several lines of evidence have linked Nlp to human cancer." (PMID 21505454, 2011). "Mitotic Neks are candidates to be considered in the next wave of targets because Nek2, -6, and -7 overexpression is associated with several cancers." (PMID 19941817, 2009).
cancer (continued). "Spliceosome-associated SR protein kinases SRPKs, CLKs, and NEK2 are altered in many cancers." (PMID 40470182, 2025). "Moreover, the expression of NEK2 is highly linked to cancer occurrence, development, and drug resistance." (PMID 38706902, 2024). "Furthermore, abnormality of NEK2 has been found to be linked to the incidence and development of many malignant tumors." (PMID 34046198, 2021). "NEK2 up-regulation in cancer cells was previously associated with its localization in the nucleus." (PMID 34930366, 2021). "NEK2 localizes in the nucleus and promotes oncogenic splice variants in different cancer cells." (PMID 34930366, 2021). "Therefore, the association between the overexpression of TRF1 and NEK2 is a mechanism that protects cells against aneuploidy and is related to cancer cell progression." (PMID 33673578, 2021). "However, more recent evidence indicates that this kinase accumulates in the nucleus of cancer cells, interacts with splicing factors and promotes pro-tumoral splice-variants, but the possible function of NEK2 in the nucleus of BC cells is currently unexplored." (PMID 34930366, 2021). "NEK2 is associated with drug resistance in multiple cancers." (PMID 31955515, 2020). "High expression of NEK2 is associated with poor survival in various cancers." (PMID 28086949, 2017). "Similar to Nek2, Nek6 is overexpressed in tumors from a variety of tissues including breast, uterus, colon, ovary, thyroid, and cervix, as well as a number of associated carcinoma cell lines." (PMID 22040655, 2011). "Thus, this study in Drosophila provides insight into how Nek2 alone, as well as when combined with oncogenic mutations, promotes invasive properties, which is relevant to the understanding of Nek2-overexpressing human cancers." (PMID 29693007, 2018). "NEK2 overexpression has been identified in a wide range of human cancers and enhances malignancy through multiple pathways." (PMID 41535675, 2026). "Our results comprehensively characterize the role of NEK2 in Rb tumorigenesis and identify a druggable target for Rb and other cancers with NEK2 overexpression." (PMID 41535675, 2026). "For example, small-molecule inhibitors targeting NEK2 have demonstrated efficacy in disrupting centrosome dynamics, leading to mitotic arrest and apoptosis in cancer cells." (PMID 41154634, 2025). "The central challenge for NEK2 inhibitors is to achieve a therapeutic window that allows for the killing of cancer cells (which are often more dependent on a properly functioning mitotic apparatus) without causing unacceptable side effects." (PMID 41154634, 2025). "NEK2 inhibitors aim to impair centrosome separation and mitotic progression, leading to cell cycle arrest and apoptosis in cancer cells." (PMID 41154634, 2025). "The overexpression of NEK2 in cancer leads to chromosomal instability and tumor progression and is associated with increased proliferation, angiogenesis, metastasis, and drug resistance." (PMID 40564876, 2025). "NEK2 is overexpressed in multiple cancers, including breast, ovarian, prostate, cervical cancer, and leukemia." (PMID 41256331, 2025). "The development and clinical evaluation of NEK2 inhibitors in human cancers have emerged as a promising therapeutic strategy." (PMID 40076620, 2025). "Subsequently, the group further developed TAI95 as a first-in-class oral clinical candidate for NEK2/HEC1 inhibition with potential for cancer therapy." (PMID 40076620, 2025). "Despite its promise as a cancer target, the fundamental role of NEK2 in mitosis raises significant concerns about toxicity in healthy proliferating tissues, such as bone marrow and the intestinal epithelium." (PMID 41154634, 2025). "Studies have shown that INH1 decreases the protein level of NEK2 and inhibits cancer cell growth in vivo and in vitro." (PMID 38795132, 2024).
cancer (continued). "While NEK2 is essential for cell cycle progression of normal cells, it is frequently overexpressed in cancer, thereby potentially opening a specific therapeutic window." (PMID 38182898, 2024). "Disruption of the NEK2–RhoGDI1 interaction through overexpression of a RhoGDI1 truncated fragment (aa 112–134) led to diminished RhoGDI1 phosphorylation and RhoA/Rac1 activation induced by NEK2, resulting in reduced cancer cell proliferation and migration." (PMID 39768163, 2024). "This study indicates that NEK2 promotes the metastatic behaviors of cancer cells by activating RhoA and Rac1 by phosphorylating RhoGDI1." (PMID 39768163, 2024). "In STAD, NEK2 has been shown to play a cancer-promoting role by activating the AKT-mediated signaling pathway." (PMID 38706902, 2024). "In this study, we provide evidence suggesting a novel mechanism by which NEK2 regulates cancer cell growth and motility." (PMID 39768163, 2024). "Recent studies have highlighted NEK2’s role in regulating the migration and invasion of cancer cells." (PMID 39768163, 2024). "Previous report demonstrated that, NEK2 is necessary to maintain the transformed phenotype of cancer cells and regulate the transforming growth, survival and chemoresistance of tumors." (PMID 38721812, 2024). "Evidence suggests that the level of NEK2 is upregulated in primary tumor tissues or cancer cell lines." (PMID 35880695, 2023). "NEK2 is known to influence cancer progression by affecting the activation of pro-tumourigenic signalling pathways, such as Akt, Wnt/β-catenin or MAPK, in multiple types of cancers." (PMID 37100815, 2023). "Altogether, KMPlot and the literature for NEK2 has revealed it to be a potential target for small molecule therapeutics in recurring ovarian and other aggressive cancers." (PMID 37046733, 2023). "The results showed that the Wnt signaling pathway and cancer signaling pathway were significantly enriched in the NEK2 high expression group." (PMID 37233832, 2023). "The oncogenic functions of NEK2 have been recently discovered while many studies have reported that its expression increases in plethora of malignant tumors and is related to poor survival rates and unfavorable results." (PMID 37600577, 2023). "Although NEK2 has previously been shown to interact with many other genes while demonstrating its involvement in cancer treatment within the ovary." (PMID 37550786, 2023). "NEK2 is a mitotic kinase that is frequently upregulated in human cancers, where it contributes to malignancy and drug resistance." (PMID 35530315, 2022). "For instance, phosphorylation by the SRPK1, AURKA, and NEK2 kinases was shown to enhance the splicing activity of SRSF1 in multiple cancer cell types." (PMID 35530315, 2022). "The copy number of NEK2 was also amplified and NEK2 mRNA levels were increased in TP53Del samples from these cancer types, except for LIHC and LUAD." (PMID 35088582, 2022). "The newly developed compound preserved the previously observed mechanism of action towards Hec1 and Nek2 and sensitized a wide array of cancer cells including several multidrug-resistant cell lines, such as MES-SA/Dx5, NCI-ADR-RES, and K562R." (PMID 35056661, 2022). "Accumulating evidence reveals that NEK2 is upregulated in a variety of cancer tissues and cell lines, indicating the involvement of NEK2 in tumorigenesis." (PMID 35031599, 2022). "INH154 was further found to be effective in sensitizing cancer cell-lines with elevated levels of Hec1 and Nek2, as demonstrated by the suppression of tumor growth in mouse xenografts." (PMID 35056661, 2022). "This compound is currently being investigated in clinical trials as a potential anti-cancer therapy for sensitizing the HEC1/Nek2 axis." (PMID 35056661, 2022). "Given the ubiquitous expression of Sam68 and NEK2 and their frequent upregulation in different cancer types, their interaction is likely functional also in other tumors." (PMID 35530315, 2022).
cancer (continued). "Several studies have emerged in which downregulation or inhibition of the Nek2 kinase function has resulted in the attenuation of Wnt/β-Catenin signaling in several types of cancers." (PMID 35056661, 2022). "There is increasing appreciation that NEK2 plays a pivotal role in cancer cell proliferation and stemness." (PMID 35711835, 2022). "Upregulation of TTK, NEK2, and CDK1 was associated with growth factor-initiated signaling, i.e., salvage pyrimidine and purine pathways are frequently deregulated in cancer." (PMID 34072728, 2021). "Prior studies have noted the pivotal cancer-promoting function of NEK2 in cancer, which has different mechanisms among different cancer types." (PMID 34168996, 2021). "A member of the serine/threonine kinase protein family NEK2 also shows overexpression in multiple cancer types which is indicative of relapse and poor survival." (PMID 34728699, 2021). "NEK2 is highly expressed in various tumor types and cancer cell lines with rapid relapse and poor outcome." (PMID 34818353, 2021). "Previous evidence has shown that overexpression of NEK2 in various human cancers is well correlated with processes of cancer progression, including chromosomal instability, high proliferation, drug resistance, and metabolism." (PMID 34168996, 2021). "NEK2 has been highlighted as an oncogenic gene in various types of human cancers and is considered to be a potential therapeutic approach for human cancer treatment." (PMID 34681056, 2021). "In the present study, NEK2 has been identified as another critical regulatory factor in cancer immune resistance." (PMID 34315872, 2021). "Nek2 inhibition decreases tumor cell proliferation and resensitizes cancer cells to chemotherapeutic agents." (PMID 33907253, 2021). "Bioinformatic analyses across multiple cancers demonstrated that NEK2 is the most significantly upregulated member of the NEK family in PAAD compared with expression in normal tissues." (PMID 34315872, 2021). "NEK2 has been proposed as a promising target in cancer therapy, and various drugs are currently under development." (PMID 33917186, 2021). "The present study identified a novel function of Nek2 that will undoubtedly advance our understanding of its ever-growing importance in cancer biology." (PMID 33907253, 2021). "Abnormal proliferation is characteristic of Malignant tumors, and in vitro proliferation assay further validated the role of NEK2 in the proliferation of DLBCL cells." (PMID 34168996, 2021). "Studies have shown overexpression of NEK2 in several human cancers, acting in malignant transformation, tumor progression, metastasis, and drug resistance." (PMID 33673578, 2021). "In TGCTs, NEK2 was found enriched in the nucleus of several cancer cells, including testicular seminomas, where it interacts with and phosphorylates numerous splicing factors, including the oncogenic SR protein SRSF1." (PMID 34440480, 2021). "These experimental data, therefore, suggest that NEK2 exerts its pro-cancer effect through PKM2 in DLBCL." (PMID 34168996, 2021). "NEK2 plays a role in developing drug resistance against various anti-cancer drugs, including 5-fluorouracil and sorafenib." (PMID 33917186, 2021). "An oncogenic kinase that is frequently upregulated in cancer, including BC, is the NIMA related kinase 2 (NEK2)." (PMID 34930366, 2021). "Nek2 is a serine/threonine kinase involved in the regulation of several aspects of mitosis that is overexpressed in several cancers, making it an intriguing antineoplastic drug target (anticancer Nek2 inhibitors are reviewed by Fang and Zhang)." (PMID 34299488, 2021).
cancer (continued). "Previous data from our group and others have indicated that NEK2 is overexpressed in various cancers, including MM, cholangiocarcinoma, testicular seminomas, human breast cancer, cervical cancer, prostate cancer, and colorectal cancer." (PMID 31955515, 2020). "Previous studies have found NEK2 to play roles in chromosome instability, tumorigenesis, cancer progression, and drug resistance." (PMID 32504181, 2020). "A considerable number of studies linking NEK2 to cancer and other disorders have been published in the literature, and these are presented in this review." (PMID 32294979, 2020). "Dysregulations of the NEK2 and PIM1-3 kinase signaling axes have been implicated in the pathogenesis of several cancers, including those with a neuroendocrine phenotype." (PMID 32504181, 2020). "Subsequently, more and more evidence has indicated that NEK2 is overproduced in various human cancers and participates in malignant transformation, including tumor progression and metastasis, drug resistance." (PMID 32907622, 2020). "NIMA‐related kinase 2 (NEK2) is a kind of mitotic kinases involved in carcinogenesis and development of various cancers." (PMID 32558224, 2020). "Studies have confirmed that NDC80 and CEP250, in connection with NEK2, participated in the mechanism of some cancers." (PMID 33109182, 2020). "It has also been documented that NEK2 depeltion impairs cancer cell drug resistance through inhibition of the PP1/AKT/NF-κB signaling pathway in multiple myeloma." (PMID 32907622, 2020). "NEK2 is overexpressed in a variety of malignant tumors and is closely related to tumor drug resistance, rapid recurrence, and poor prognosis." (PMID 33408736, 2020). "Although dysregulations of the NEK2, PIM1, and PIM3 kinase signaling axes have been implicated in the pathogenesis of several cancers, including those with a neuroendocrine phenotype, their role in the pathogenesis of BP-NENs has not been determined." (PMID 32504181, 2020). "The Cancer Dependency Map Portal reports that SCLC cell lines demonstrate low to moderate dependency on knockout of NEK2." (PMID 32504181, 2020). "Previous studies have demonstrated the regulation of β-catenin by Nek2 at mitotic centrosomes, but few studies have also shown a possible correlation between Nek2 and β-catenin in cancer." (PMID 31319849, 2019). "Our work also calls for the development of a selective kinase inhibitor to better explore the function of Nek2 in cancer." (PMID 31319849, 2019). "As a transcription factor, FOXM1 has many target genes including KIF20A, CENPF, CCNB1, MYC, NIMA-related kinase 2, MMP2, MMP9, and S-phase kinase-associated protein 2 that are implicated in cancer initiation, progression, or drug resistance." (PMID 31072351, 2019). "A recent study demonstrates that overexpression of NEK2 and drug resistance are closely correlated in other cancers through activation of efflux drug pumps." (PMID 35582716, 2019). "High expression of NEK2 promoted a higher efflux of the hydrophilic eFluxx-ID gold fluorescent dye from cancer cells." (PMID 35582716, 2019). "NEK2 regulates tumor progression, drug resistance and tumorigenesis, which is considered to be a potential biomarker of cancers." (PMID 31519156, 2019). "Overexpression of Nek2 is common in human cancers and suppression can restrict tumor cell growth and promote apoptosis." (PMID 27833088, 2017). "We have demonstrated that high NEK2 expression induces chromosomal instability and cancer cell proliferation." (PMID 28086949, 2017). "Kaplan-Meier survival curves show that higher expression of NEK2 and MYBL2 is also associated with worse clinical outcomes in various cancers." (PMID 28427185, 2017).